KIT (KIT proto-oncogene, receptor tyrosine kinase)
Diseases named in the same sentence as KIT in open-access papers (continued):
Sharing a sentence is not in itself a finding about the gene and the disease.
systemic mastocytosis (134 papers, 2004 to 2026). Systemic mastocytosis (SM) comprises a heterogeneous group of rare acquired and chronic hematological malignancies that are related to an abnormal proliferation of mast cells in tissue, including bone marrow, with or without skin involvement. "Systemic mastocytosis (SM) is defined by excessive MC accumulation in tissues because of a somatic gain-of-function mutation in the KIT gene, which hinders MC normal apoptosis and induces MC proliferation." (PMID 39976807, 2025). "Given the subsequent diagnosis of systemic mastocytosis and detection of the KIT D816V mutation, we infer that clinically occult mast cell proliferation was already present at the time of the reaction." (PMID 41568380, 2025). "By inhibiting the mutated KIT protein, bezuclastinib aims to reduce the mast cell burden and alleviate the symptoms associated with systemic mastocytosis." (PMID 41009465, 2025). "In this context, systemic mastocytosis is most often a clonal disorder driven by somatic activating mutations in the KIT gene." (PMID 41177946, 2025). "Systemic mastocytosis is a rare, clonal mast cell disease neoplasm driven by the KIT D816V mutation in greater than 95% of cases." (PMID 41244098, 2025). "In humans, the most common KIT-activating mutation found in more than 80% of adults with systemic mastocytosis is D816V in exon 17 of the TKD2." (PMID 39728933, 2024). "We identified heterozygous and homozygous recessive KIT M541L variants in 19 adult and pediatric patients with cutaneous and systemic mastocytosis." (PMID 39037378, 2024). "Overall, the KIT M541L variant was identified in 19 individuals; the majority were diagnosed with systemic mastocytosis (89.4%) with an associated KIT D816V mutation." (PMID 39037378, 2024). "We further found a higher prevalence of this variant in patients with systemic mastocytosis with an associated KIT D816V mutation." (PMID 39037378, 2024). "Other activating mutations, such as KIT V560G in the juxtamembrane domain and KIT D419del in the extracellular domain, are less common but found in patients with aggressive systemic mastocytosis (ASM), mast cell leukemia (MCL), and mast cell sarcoma." (PMID 39456668, 2024). "A point mutation in codon 816 of the KIT gene (KIT D816V) is typically found in adults with systemic mastocytosis." (PMID 36766791, 2023). "The microphthalmia-associated transcription factor (MITF) is highly expressed in bone marrow biopsies from 9 of 10 patients with systemic mastocytosis and activating KIT mutations." (PMID 36834926, 2023). "This review outlines the range of mast cell disorders, with a focus on systemic mastocytosis, a rare clonal neoplastic mast cell proliferation in various tissues, often associated with KIT mutations that cause uncontrolled mast cell growth." (PMID 38067330, 2023). "Over 90% of people with systemic mastocytosis have a CD117 gene mutation [KIT (D816V) mutation], resulting in receptor sending out signals continuously." (PMID 37159631, 2023). "There is a possibility of using mTOR inhibitors like rapamycin for patients expressing D816V-mutated KIT in aggressive systemic mastocytosis." (PMID 36766791, 2023). "Based on the results of clinical trials, the FDA approved its indications in FLT3-mutated AML and KIT-mutated systemic mastocytosis patients in 2017." (PMID 36230769, 2022). "Midostaurin was approved by the US FDA and the European Medicines Agency for both newly diagnosed FLT3-mutated AML and advanced systemic mastocytosis (SM) driven by KIT mutation." (PMID 35211416, 2022). "The receptor tyrosine kinase KIT, a mast cell signature protein, has been associated with circulating EVs from patients with systemic mastocytosis, acute myeloid lymphoma, EVs released by neoplastic mast cells, activated mast cells, and GIST cells." (PMID 36239715, 2022). "In more than 80% of subjects with systemic mastocytosis (SM), a somatic point genetic mutation in KIT at codon 816 is discovered." (PMID 36009422, 2022).
systemic mastocytosis (continued). "Somatic mutations in c-KIT that code for the KIT receptor (the most common of these being the D816V mutation) have been linked to the development of systemic mastocytosis, a clonal hematological disorder." (PMID 34681933, 2021). "Somatic mutations in c-KIT that code for the KIT receptor have been linked to the development of systemic mastocytosis, a clonal hematological disorder." (PMID 34681933, 2021). "Advanced systemic mastocytosis (AdvSM) is a rare hematologic neoplasm driven by the KIT D816V mutation and associated with poor survival." (PMID 34873347, 2021). "Although more than 90% of patients with systemic mastocytosis have a mutation in codon 816 of KIT (KIT D816V), alternative KIT mutation in codon 816 (e.g., D816A/F/H/I/N/T/Y) has been described." (PMID 33687603, 2021). "Systemic mastocytosis (SM) is a clonal, multisystem disease, driven by activating KIT mutations, most commonly D816V, that leads to accumulation of neoplastic mast cells in various organs." (PMID 33804174, 2021). "More than 90% of patients with systemic mastocytosis have a gain-of-function mutation in codon 816 of the receptor tyrosine kinase KIT, where a valine is substituted for an aspartate (KIT D816V)." (PMID 33687603, 2021). "Activating mutations in KIT are detected in most cases of systemic mastocytosis, being the most common KIT D816V." (PMID 32346366, 2020). "Advanced systemic mastocytosis (advSM) is characterized by the presence of an acquired KIT D816V mutation in >90% of patients." (PMID 30911112, 2019). "Primary MC activation disorders are caused by intrinsic proliferation or clonal expansion of MCs and are associated typically with KIT mutations, represented by cutaneous or systemic mastocytosis (CM or SM) and monoclonal MCAS." (PMID 31336653, 2019). "Patients with such so-called well-differentiated systemic mastocytosis (WDSM) harbored low frequency of KIT D816V mutation compared with other forms of SM (29% vs. 93%)." (PMID 29088753, 2017). "Resistance to imatinib has been recurrently reported in systemic mastocytosis (SM) carrying exon 17 KIT mutations." (PMID 28978170, 2017). "Most cases of systemic mastocytosis are associated with a gain-of-function mutation in the KIT (CD117) tyrosine kinase, usually a D816V mutation." (PMID 27648315, 2016). "Systemic mastocytosis (SM) is frequently associated with gain-of-function mutations in codon 816 (D816V) of KIT, the tyrosine kinase receptor for stem cell factor (SCF)." (PMID 27611333, 2016). "The majority of systemic mastocytosis patients carry KIT D816V mutation, which activates constitutively the KIT receptor." (PMID 27783996, 2016). "In systemic mastocytosis (SM), a gain-of-function mutation in the tyrosine kinase receptor (KIT D816V) contributes to cell-autonomous proliferation of atypical mast cells." (PMID 25894969, 2015). "Both patients with systemic mastocytosis had previously tested positive for the presence of a KIT mutation by allele-specific PCR (KIT D816V)." (PMID 25894969, 2015). "More than 90% of human patients with systemic mastocytosis carry the D816V mutation in KIT which results in constitutive activation of KIT signaling and plays a major role in the proliferative phenotype." (PMID 24517413, 2014). "KIT mutations occur in the vast majority of systemic mastocytosis (SM) and subsets of acute leukemia, including core-binding factor (CBF) and pediatric AML." (PMID 23497317, 2013). "The inhibitory activity of midostaurin against c-KIT is also of interest because of the role that mutations in c-KIT play in aggressive systemic mastocytosis (ASM)." (PMID 22294470, 2012). "Systemic mastocytosis (SM) typically occurs in adults with c-KIT D816V mutation." (PMID 41836292, 2026). "Furthermore, systemic mastocytosis (SM), a rare condition, is characterized by a KIT D816V mutation in approximately 95% of cases." (PMID 40336047, 2025).
systemic mastocytosis (continued). "A recent study confirmed a strong correlation between blood and bone marrow KIT p.D816V allele burden, demonstrating that the presence of KIT p.D816V in peripheral blood, which is a minor criterion for the diagnosis of systemic mastocytosis, is highly specific for CMD." (PMID 40397530, 2025). "A case report of feline systemic mastocytosis and mastocytemia with a mutation in exon 8 of KIT detailed a favourable response to treatment with imatinib, with the tumour masses undetectable after 5 weeks of treatment and the number of mast cells in the peripheral blood markedly reduced." (PMID 38787171, 2024). "Most patients (>95%) with systemic mastocytosis (SM) carry a mutation in the KIT gene (KIT D816V)." (PMID 38339343, 2024). "Additionally, KIT mutations involving codon 560 in exon 11 and codons 815, 816, and 820 in exon 17 have been described in adult systemic mastocytosis, while E839K has been reported in pediatric mastocytosis." (PMID 39728933, 2024). "Moreover, MITF is highly expressed in bone marrow biopsies from patients with systemic mastocytosis and activating KIT mutations." (PMID 37234172, 2023). "Systemic mastocytosis is a rare, clonal mast cell neoplasm driven by the KIT D816V mutation that is characterized by uncontrolled proliferation and activation of mast cells, which leads to severe and unpredictable symptoms for patients with systemic mastocytosis." (PMID 36964624, 2023). "Indeed, the gene encoding the KIT protein, c-Kit, is considered a proto-oncogene and activating mutations are known to induce the development of cutaneous or systemic mastocytosis—the abnormal accumulation of MCs within tissues." (PMID 36798116, 2023). "In this article, we elaborate on recent data pertaining to minor diagnostic criteria of systemic mastocytosis (SM), including sensitive testing methods for detection of activating mutations in the KIT gene or its variants, and adjusted serum tryptase levels in cases with hereditary α-tryptasemia." (PMID 35884535, 2022). "Systemic mastocytosis (SM) is a clonal haematopoietic stem cell disease typically characterized by the expansion and accumulation of neoplastic mast cells carrying the activating KIT D816V as a driver mutation." (PMID 35626091, 2022). "In the present study, we found that midostaurin, a clinically available therapeutic agent against FLT3-mutated AML and KIT-mutated systemic mastocytosis, may be repositioned to an enhancer for anti-PD-1 against colon cancer." (PMID 36230769, 2022). "On the basis of clinical evidence, primarily in GIST, AML and systemic mastocytosis, KIT-activating alterations are associated with sensitivity to KIT tyrosine kinase inhibitors (TKIs) including imatinib, sunitinib, sorafenib, dasatinib, nilotinib, ponatinib, midostaurin and avapritinib." (PMID 36551764, 2022). "Systemic mastocytosis is a rare, clonal mast cell neoplasm driven by the KIT D816V mutation, characterized by uncontrolled proliferation and activation of mast cells that leads to severe and unpredictable symptoms for patients with systemic mastocytosis." (PMID 34663404, 2021). "Patients with systemic mastocytosis (SM), whose MCs frequently arbor the activating D816V KIT mutation, may have indolent to aggressive diseases, and they may experience MC mediator related symptoms." (PMID 28439288, 2017). "Activating mutations in the receptor tyrosine kinase encoding c-KIT gene have been observed in systemic mastocytosis (SM), a rare MPD characterized by the infiltration of the clonally derived mast cells into a variety of different tissues including bone marrow." (PMID 25884214, 2015). "Acquired mutations in KIT are driver mutations in systemic mastocytosis (SM)." (PMID 25026279, 2014). "In myeloid neoplasms (MNs), KIT mutation is primarily correlated with systemic mastocytosis (SM), with 90% patients harboring activating mutation and KIT D816V occurred most frequently." (PMID 41557053, 2026).
systemic mastocytosis (continued). "Systemic mastocytosis (SM) is an uncommon illness characterized by the multiorgan accumulation of clonal MCs that differentiate less dependently on the natural KIT ligand (SCF) because of somatic mutations in c-KIT (D816V mutation presents in over 90% of adult patients)." (PMID 40175843, 2025). "Mutations in the tyrosine kinase domain of KIT are detected frequently in systemic mastocytosis (SM), ENKL, and seminomas." (PMID 35563085, 2022). "In systemic mastocytosis (SM), qualitative and serial quantitative assessment of the KIT D816V mutation is of diagnostic and prognostic relevance." (PMID 33806359, 2021). "Systemic mastocytosis (SM) is a rare hematologic neoplasm that is associated with the KIT D816V mutation in ~95% of cases." (PMID 34873345, 2021). "Systemic mastocytosis (SM) is a rare clonal hematologic neoplasm, driven, in almost all cases, by the activating KIT D816V mutation that leads to the growth and accumulation of neoplastic mast cells." (PMID 33804174, 2021). "In >80% of patients with systemic mastocytosis (SM), a somatic point mutation in KIT at codon 816 is found." (PMID 31216696, 2019). "One patient with KIT D816V-positive systemic mastocytosis with associated hematologic neoplasm (SM-AHN) responded to midostaurin but the response was lost after 9 months." (PMID 30573779, 2019). "The majority of adult patients with systemic mastocytosis (SM) has aberrant mast cell morphology such as spindle shapes and hypogranulation, and harbor the KIT D816V mutation." (PMID 29088753, 2017). "Neoplastic accumulation of mast cells in systemic mastocytosis (SM) associates with activating mutations in the receptor tyrosine kinase KIT." (PMID 27611333, 2016). "It suggests that avapritinib may bridge therapeutic gaps for atypical KIT-mutant systemic mastocytosis with associated hematologic neoplasm (SM-AHN) that is ineligible for Allo-HSCT or relapsed." (PMID 41473436, 2025). "Avapritinib, a potent and selective inhibitor of KIT D816V, is approved for treating advanced systemic mastocytosis(AdvSM)." (PMID 40623907, 2025). "Midostaurin, an inhibitor of several Type III tyrosine kinase receptors, is approved for newly diagnosed adult patients with FLT3-mutated AML and advanced systemic mastocytosis (SM), especially MCL with KIT D816 mutations." (PMID 41199910, 2025). "We also want to evaluate whether the KIT p.D816V mutation in peripheral blood leukocytes (PBLs) reliably predicts systemic mastocytosis (SM) in children." (PMID 40649802, 2025). "Existing therapies such as tyrosine kinase inhibitors (e.g., imatinib), which suppress c-KIT-mediated mast cell activation, have been used to treat systemic mastocytosis." (PMID 39950116, 2025). "In most patients with advanced systemic mastocytosis (AdvSM), neoplastic mast cells (MC) express KIT D816V." (PMID 35804842, 2022). "In a phase 1 trial of patients with advanced systemic mastocytosis, avapritinib, a selective KIT inhibitor, was generally well tolerated, elicited durable clinical responses and led to reductions in mast cell disease burden." (PMID 34873347, 2021). "Advanced systemic mastocytosis (AdvSM) is a rare, KIT D816V-driven hematologic neoplasm characterized by mast cell infiltration and shortened survival." (PMID 34873345, 2021). "Correspondingly, patients with indolent systemic mastocytosis, where KIT D816V is usually the only driver lesion, accumulate their mast cell aggregates over years or even decades, and have a stable disease course with normal life expectancy." (PMID 30759825, 2019). "In advanced systemic mastocytosis, drugs targeting the oncogenic KIT D816V mutant have been developed." (PMID 30759825, 2019). "LADR and LAD2 cells do not harbor mutations in KIT, expressed by as much as 80% of patients with systemic mastocytosis (SM), representing a disadvantage of this cell line for studying emerging therapeutics directed at KIT D816V." (PMID 31698677, 2019).
systemic mastocytosis (continued). "Activating D816 mutations of the class III receptor tyrosine kinase KIT are associated with the majority of patients with systemic mastocytosis (SM), but also core binding factor (CBF) AML, making KIT mutations attractive therapeutic targets for the treatment of these cancers." (PMID 29137311, 2017). "To conclude, this new in vivo model mimics at the best the features of human KIT D816V+ advanced systemic mastocytosis." (PMID 27783996, 2016). "Activating KIT mutations are part of the pathogenesis of systemic mastocytosis (SM)." (PMID 26002753, 2015). "This variant (c.1621 A > C) in exon 10 of KIT (KITL541) has previously been described in CML, AF, systemic mastocytosis and Merkel cell carcinoma." (PMID 26498480, 2015). "In this study, we used a combination of in vitro and in vivo models to investigate a role for TET2 in the pathogenesis of KIT D816V-positive systemic mastocytosis." (PMID 24788138, 2014). "Avapritinib is established for KIT D816V-mutant advanced systemic mastocytosis (AdvSM)." (PMID 41473436, 2025). "Recently, Naumann and colleagues, by analyzing a large number of samples, demonstrated that in patients with indolent systemic mastocytosis there is a high level of concordance between KIT p.D816V VAF and EAB, but in patients with AdvSM this correlation is weak." (PMID 39456668, 2024). "Similarly, worsening cytopenias were observed with the use of KIT inhibitors in advanced systemic mastocytosis, and the CRh category was introduced to the modified IWG response criteria used in the evaluation of avapritinib in advanced systemic mastocytosis." (PMID 37076693, 2023). "MML is another important differential diagnosis of SM, especially when systemic mastocytosis with an associated hematological neoplasm or MCL with a lack of KIT codon 816 mutations is suspected." (PMID 29458385, 2018). "In two cases, (imatinib/KIT for aggressive systemic mastocytosis and imatinib/platelet-derived growth factor receptor B for myelodysplastic syndrome–myeloproliferative disease), the drug approval was supported by only case reports, so data on the interaction were not available." (PMID 28761069, 2017). "Whereas KIT D816V/H mutation is a well-characterized oncogenic event and principal cause of systemic mastocytosis, the homologous CSF-1R D802V has not been identified in human cancers." (PMID 24828813, 2014). "Actually, KIT D816V gain-of-function mutation is a well-characterized oncogenic event and identified in more than 80% of systemic mastocytosis, whereas the equivalent CSF-1R D802V mutation has not been found in human tumors." (PMID 24828813, 2014). "Unlike GIST, in systemic mastocytosis activation of KIT is typically associated with point mutations in the enzymatic region of the molecule." (PMID 14710199, 2004). "Hence, we decided to group herein all the patients under the term “MMCS KIT 816−/+” because of the overlap with systemic mastocytosis and its complications (severe anaphylaxis, osteoporosis)–even though the disease could be considered to be less advanced." (PMID 39877259, 2025). "Midostaurin, a multikinase inhibitor with potent activity against KIT D816V, has emerged as a key therapeutic option in advanced systemic mastocytosis, including ASM, SM with an associated hematologic neoplasm, and mast cell leukemia." (PMID 40722727, 2025). "Imatinib, for instance, is an agent that preferentially kills mast cells with wild-type KIT, and therefore most patients with systemic mastocytosis are not candidates for imatinib therapy because most of them have the D816V KIT mutation, which confers resistance to imatinib." (PMID 23903270, 2013). "In rare cases of systemic mastocytosis, no KIT-D816V mutation is detected." (PMID 24141298, 2013). "Of interest, this data contrasts with our recent report on JAK2 V617F and KIT D816V in patients with concurrent diagnosis of a MPN and systemic mastocytosis." (PMID 40681596, 2025).